FABP5 (fatty acid binding protein 5)
Diseases named in the same sentence as FABP5 in open-access papers (continued):
Sharing a sentence is not in itself a finding about the gene and the disease.
diabetes (14 papers, 2011 to 2025). "Additionally, polymorphisms in FABP5 are associated with type 2 diabetes mellitus." (PMID 36292760, 2022). "Here, increasing Acot7 and Fabp5 in β-cells correlates with a normal → diabetic shift, consistent with their known overexpression in diabetes." (PMID 41465115, 2025). "We investigated concentrations of FABP4 and FABP5 in patients with type 2 diabetes mellitus who were receiving statin therapy at high risks for cardiovascular disease." (PMID 33071982, 2020). "In conclusion, circulating FABP4 and FABP5 levels are independent predictors each other in patients with type 2 diabetes mellitus." (PMID 33071982, 2020). "In addition, FABP4 and FABP5 have been shown to be involved in the pathogenesis of various diseases including diabetes mellitus (DM), hypertension (HT), hyperlipidemia (HL), renal disease, heart diseases and malignant tumors." (PMID 39273233, 2024). "We investigated concentrations of FABP4 and FABP5 in patients with type 2 diabetes mellitus." (PMID 33071982, 2020).
metabolic syndrome (14 papers, 2011 to 2025). A cluster of metabolic risk factors for CARDIOVASCULAR DISEASES and TYPE 2 DIABETES MELLITUS. "Increased serum levels of FABP5 have been shown to be associated with cardio-metabolic risk and the metabolic syndrome in humans as well." (PMID 23349676, 2013). "Determining whether treating the metabolic syndrome would reduce the risk of having accelerated lung function decline or whether FABP5 expression should be increased in airway epithelial cells to prevent COPD exacerbations would be of major importance to find a sustainable treatment for COPD." (PMID 23349676, 2013). "FabPs play roles in fatty acid uptake, transport and metabolism; FabPs expressed by adipocytes and macrophages (FabP4 and FabP5, respectively) play key roles in regulating systemic metabolism and are important mediators of metabolic syndromes in mice." (PMID 22216095, 2011). "Fabp5 is expressed in many tissues including the liver and studies in mice null for both Fabp4 and Fabp5 demonstrate a role for Fabp5 in systemic glucose and lipid homeostasis as these mice are substantially protected from the metabolic syndrome." (PMID 24551121, 2014). "Moreover, aberrant FABP5 indicate metabolic abnormalities which may result in the development of metabolic syndrome and cardiovascular diseases." (PMID 34131888, 2021). "However, circulating FABP5, similar to FABP4, has been reported to be detected at levels of about one tenth or less of FABP4 concentrations, and FABP5 level has been shown to be associated with components of metabolic syndrome, though the correlation is not as strong as that of FABP4." (PMID 27936164, 2016). "In the other studies serum FABP5 levels correlated positively with parameters of adiposity, adverse lipid profiles, serum insulin, adipocyte fatty acid binding proteins (A-FABP, FABP4), C-reactive protein levels and were higher in subjects with the metabolic syndrome (MS)." (PMID 34131888, 2021). "Secondly, as far as we surveyed, a relationship between FABP5 and UPR has not been identified, although FABP4, which is a critical indicator for various metabolic syndromes as is FABP5, has been shown to be importantly involved in UPR." (PMID 39273233, 2024).
triple-negative breast carcinoma (14 papers, 2014 to 2025). An invasive breast carcinoma which is negative for expression of estrogen receptor (ER), progesterone receptor (PR), and human epidermal growth factor receptor 2 (HER2). "Following this finding, other correlations were done between FABP5 over-expression and association with poor survival and triple-negative breast cancer." (PMID 32012980, 2020). "In addition, up-regulation of FABP5 was strongly associated with poor survival in triple-negative breast cancer." (PMID 32579175, 2020). "For instance, a recent study published in Science demonstrated that LA promotes the growth of triple-negative breast cancer by activating the FABP5-mTORC1 signaling axis." (PMID 40371224, 2025). "FABP5 has been previously identified as being pro-tumorigenic in retinoic acid signaling in triple negative breast cancer (TNBC) patients." (PMID 25779666, 2015). "We previously showed that FABP5 is preferentially expressed in ER- and triple-negative breast cancers, molecular subtypes believed to be resistant to RA treatment." (PMID 26142905, 2015). "The objective of this research was to investigate the effect of curcumin, a polyphenol extract from the plant Curcuma longa, on the FABP5/ PPARβ/δ pathway in retinoic acid resistant triple negative breast cancer cells." (PMID 25260874, 2014). "Our data demonstrates that suppression of the FABP5/ PPARβ/δ pathway by curcumin sensitizes retinoic acid resistant triple negative breast cancer cells to retinoic acid mediated growth suppression." (PMID 25260874, 2014). "Also, FABP5 is critical in metastatic transformation and stromal cell interactions for triple-negative breast cancer." (PMID 36338999, 2022). "However, a recent paper found conflicting result related to FABP5/CRABPII ratio implication on ATRA sensitivity in triple-negative breast cancer, so that further data are needed, especially for other solid cancer types than breast." (PMID 32012980, 2020). "We propose that these three RA-binding proteins can serve as biomarkers for predicting triple-negative breast cancer response to RA, with elevated levels of either cytoplasmic CRABP1 or FABP5 associated with RA resistance, and elevated levels of nuclear CRABP2 associated with sensitivity to RA." (PMID 26142905, 2015). "Curcumin suppresses the expression of FABP5 and PPARβ/δ, thereby overcoming the resistance to retinoic acid in MDA-MB-231 and MD-MB-468 cell lines (triple-negative breast cancer)." (PMID 39770516, 2024). "In triple negative breast cancer (TNBC), FABP5 has been found to promote metastasis by inhibiting EGFR proteasome degradation." (PMID 37576389, 2023). "Like FABP5, CRABP1 is preferentially expressed in ER- and triple-negative breast cancer." (PMID 26142905, 2015). "However, FABP5 and its role in triple negative breast cancer (TNBC) have not been studied." (PMID 25779666, 2015). "The data showed that high expression of FABP5 tended to distribute in grade III, estrogen receptor negative and triple negative breast cancer patients (p = 0.036, 0.032 and 0.001, respectively)." (PMID 29914512, 2018).
type 2 diabetes (14 papers, 2011 to 2024). "In patients with type 2 diabetes receiving statin therapy, an independent association was found between serum FABP5 concentration and low HDL cholesterol." (PMID 39456672, 2024). "Fatty acid binding protein 5 (FABP5) plays a role in fatty acid uptake, transport and metabolism and polymorphisms in this gene are associated with type 2 diabetes." (PMID 22498030, 2012). "Additionally, polymorphisms in human FABP5 are associated with type 2 diabetes." (PMID 24551121, 2014).
lymph node metastasis (12 papers, 2015 to 2025). "FABP5 was associated with some adverse prognostic factors in HNSCC such as T stage and lymph node metastasis." (PMID 39928282, 2025). "FABP5 overexpression was associated with poorer overall survival (OS), larger tumor size, advanced UICC stage, and increased risk of vascular invasion and lymph node metastasis." (PMID 40178066, 2025). "Previous work has suggested that high expression of FABP5 is positively correlated with the existence of lymph node metastasis in CC." (PMID 37056351, 2023). "The expression of FABP5 was related to lymph node metastasis (p = 0.032), the depth of invasion (p = 0.041), and the AJCC stage (p = 0.013)." (PMID 34632074, 2021). "In nude mice with lymph node metastasis, FABP5 knockdown resulted in a higher survival." (PMID 37056351, 2023). "Interestingly, patients with lymph node metastasis had higher levels of serum FABP5, as measured by ELISA30." (PMID 28211531, 2017). "High FABP5 expression correlates with worse recurrence-free survival in patients with and without lymph node metastasis (respectively)." (PMID 25779666, 2015).
liver cancer (11 papers, 2018 to 2025). An epithelial or non-epithelial malignant neoplasm that arises from the liver. "For example, FABP5 is significantly overexpressed in liver cancer and is closely associated with cell cycle regulatory genes (CDK1, CDK4) and apoptosis inhibitory genes (BIRC5)." (PMID 40717587, 2025). "Our study found that FABP5 expression was elevated in liver cancer tissues and HCC-animal models after RFA treatment, suggesting that FABP5 is associated with poor liver cancer prognosis." (PMID 39871325, 2025). "The TCGA and ICGC databases suggested that high FABP5 expression was associated with poor prognosis in liver cancer, which was positively correlated with macrophage infiltration in HCC, especially M2 macrophages." (PMID 39871325, 2025). "We found that the tumor cell death and antitumor effects caused by MELK knockdown combined with liver cancer thermal ablation may be closely related to FABP5 expression." (PMID 39871325, 2025). "However, some studies report contrasting findings, such as reduced FABP5 expression levels in pancreatic cancer, and evidence suggesting that FABP5 overexpression in liver cancer is associated with prolonged OS and disease‐free survival (DFS)." (PMID 40178066, 2025). "We further explored the clinical relevance of FABP5 in HCC by analyzing two clinical liver cancer databases and examining clinical samples, which showed that the high expression of FABP5 in patients with liver cancer, compared with peritumoral areas." (PMID 39871325, 2025). "For example, Orlistat inhibits FABP1 activity to enhance immunotherapy efficacy in HCC, BMS309403 targets FABP4 to inhibit ovarian cancer metastasis and enhance chemosensitivity, and SBFI-26 induces ferroptosis in liver cancer cells by inhibiting FABP5." (PMID 40717587, 2025). "FABP5 was over-expressed in renal clear cell carcinoma and liver cancer and, conversely, down-regulated in lung, breast and colon cancer." (PMID 37416772, 2023). "FABP5 is considered an important oncogene in liver cancer progression." (PMID 39871325, 2025). "Additionally, TIMER2.0 database analysis revealed that FABP5 expression in clinical liver cancer tissues positively correlates with infiltrating immunosuppressive cells, including M2 macrophages and myeloid-derived suppressor cells (MDSCs), but not with M1 macrophages." (PMID 41035647, 2025). "We also computationally simulated the molecular anchoring diagram of MELK and FABP5 and created an interaction diagram for FABP5 and MELK in the background based on Western blotting in SK-HEP1 and LM3 liver cancer cells." (PMID 39871325, 2025). "They find that oleic-acid treatment activates the FABP5/HIF-1α axis, promoting lipid accumulation and cell proliferation in liver cancer cells." (PMID 33128030, 2020). "Moreover, Fatty Acid-Binding Protein 5 (FABP5), which regulates fatty acid transport and metabolism, is significantly elevated in liver cancer cells, protecting them from ferroptosis." (PMID 39575419, 2024). "Moreover, the expression levels of PPARα, PPARγ, FABP1, FABP4, and FABP5 were downregulated in GL22-treated xenograft tumors, indicating that GL22 exerted a significant anticancer effect against liver cancer in vivo mediated by PPAR–FABPs signaling pathway." (PMID 29880886, 2018).
lung carcinoma (10 papers, 2018 to 2026). "Western blot analysis showed that the expression level of FABP5 in macrophages was strikingly higher than in other types of cells, including endothelial cells, lung cancer cells, epithelial cells, fibroblasts, and neutrophils." (PMID 34876574, 2021). "Furthermore, 2 risk groups of patients with lung cancer, characterized by different prognoses and immune landscapes, were stratified using a risk scoring model that comprised 3 AS-related genes (CD52, FABP5, and FCGR3A)." (PMID 41731774, 2026). "It is noteworthy, however, that several reports indicate that inhibition/knockdown of FABP5 could have an opposite effect, resulting in more skin tumors and increased lung cancer metastases." (PMID 37207357, 2023). "Lung cancer: In lung cancer, CCAT1/FABP5 promotes tumor progression through mediating fatty acid metabolism and stabilizing PI3K/AKT/mTOR signaling." (PMID 40717587, 2025). "In recent years, emerging genes have been revealed to be the potential therapeutic targets of lung cancer by inhibiting the PI3K/AKT/mTOR pathway, such as SREBP, DOK7V1, HRH3, SLFN5, and FABP5." (PMID 36349192, 2022). "Later, we analysed the correlation of FABP5 expression with the OS and DFS in lung cancer patients based on TCGA database." (PMID 34431227, 2021).
bladder cancer (9 papers, 2021 to 2025). "Present studies have revealed that FABP5 plays significant roles in different types of cancers, such as lung cancer, breast cancer, bladder cancer, hepatocellular carcinoma, clear cell renal cell carcinoma, multiple myeloma and so on." (PMID 37858219, 2023). "Additionally, both in vitro and in vivo studies have revealed the activation of the PPAR signalling pathway by FABP5 in bladder cancer, underscoring its tumorigenic capacity." (PMID 39928282, 2025). "In addition, the malignant progression of bladder cancer is promoted by m6A-induced lncDBET through FABP5-mediated lipid metabolism." (PMID 37858219, 2023). "In bladder cancer, METTL14 induces lncDBET overexpression, and along with FA binding protein 5 (FABP5), it promotes lipid metabolism and the malignant progression of bladder cancer." (PMID 38721006, 2024). "It has also been proven that lncRNADBET can interact with FABP5 to activate the PPAR signaling pathway and promote lipid metabolism in cancer cells, ultimately promoting the malignant progression of bladder cancer." (PMID 39194582, 2024).
neuroblastoma (9 papers, 2019 to 2025). Neuroblastoma (NB) is the most common solid, extracranial childhood tumor. "The long non-coding RNA FAM201A encodes a short peptide NBASP that suppresses neuroblastoma carcinogenesis by down-regulating FABP5 to inactivate the MAPK pathway." (PMID 37438449, 2023). "Immunoprecipitation identified fatty acid-binding protein 5 (FABP5) as an interaction partner of NBASP that had previously been already shown to be upregulated in MYCN-amplified neuroblastoma." (PMID 38891878, 2024). "SH-SY5Y human neuroblastoma cells were used to investigate the effects of AA on FABP5 transcriptional activity." (PMID 34068550, 2021). "PPARD identified following DAT of MPN was found to be interacting with FABP5 (found in DAT of neuroblastoma cells)." (PMID 34394070, 2021). "MF6 also inhibited the promotor activity of FABP5 in human neuroblastoma cells (SH-SY5Y)." (PMID 34068550, 2021). "Furthermore, a potentiated uptake of AEA was described for FABP5-overexpressing neuroblastoma cells." (PMID 31143113, 2019). "To investigate whether FABP5 is related to αSyn oligomerization and mitochondrial impairment, we transfected FABP5 with αSyn into neuroblastoma Neuro-2A cells, and evaluated cell viability, αSyn oligomerization, cellular localization, and mitochondrial membrane potential." (PMID 33499263, 2021). "For these reasons, we chose to examine in FABP5 using SH-SY5Y cells, a human neuroblastoma cell line that can be differentiated into post-mitotic dopaminergic neuron-like cells." (PMID 38900831, 2024). "BMS309403, designed as an FABP4 inhibitor that also elicits its effects on HeLa cells that dominantly express FABP5, was shown to increase AEA in neuroblastoma cells." (PMID 31143113, 2019).
pancreatic cancer (9 papers, 2013 to 2025). "In pancreatic tumor xenograft with high fatty acid binding protein 5 (FABP5) expression and no cellular retinoic acid binding protein 2 (CRABP2) expression is resistant to the treatment with ATRA." (PMID 33572223, 2021).
glioblastoma (8 papers, 2014 to 2025). The most malignant astrocytic tumor (WHO grade IV). "The response of glioblastoma cells to RA, decitabine or the FABP5 competitive inhibitor, BMS309403, was analyzed." (PMID 25797252, 2015). "High FABP5 protein expression was evident in short term glioblastoma survivors with highly proliferating tumors compared to long term glioblastoma survivors." (PMID 25260874, 2014). "In glioblastomas, the growing list of candidate TAAs include the epidermal growth factor receptor (EGFR), tenascin-C (TNC), fatty acid binding protein 5 (FABP5), melanoma-associated antigen 3 (MAGEA3), glioma-expressed antigen 2 (GLEA2), and PHD finger protein 3 (PHF3)." (PMID 25944688, 2015). "LN18, LN428 and U251 glioblastoma cell lines are insensitive to RA treatment irrespective to their CRABP-II and FABP5 expression statuses or FABP5 inhibition." (PMID 25797252, 2015). "The failure of the three glioblastoma cells to overcome RA resistance with the FABP5 competitive inhibitor, BMS309403, further supports this notion." (PMID 25797252, 2015). "The four staining patterns of CRABP-II and FABP5 were observed among glioblastomas: CRABP-II−/FABP5−, CRABP-II−/FABP5+, CRABP-II+/FABP5− and CRABP-II+/FABP5+ and the respective profiles were expressed by 18% (2/11), 18% (2/11), 37% (4/11) and 27% (3/11) of the glioblastomas." (PMID 25797252, 2015). "Because the major components of CRABP-II and FABP5 expression did not correlate with RA sensitivity, it is possible that CRABP-II and FABP5 are not the critical determinants of RA sensitivities in glioblastoma cells." (PMID 25797252, 2015). "Because neither the CRABP-II- nor the FABP5-mediated RA signaling pathway is the key determinant of RA sensitivity in glioblastoma cells, it would be worthwhile to search for other RA-related factors that indicate RA sensitivity to enable reliable anti-glioblastoma therapy." (PMID 25797252, 2015).
Stroke (7 papers, 2024 to 2025). Sudden impairment of blood flow to a part of the brain due to occlusion or rupture of an artery to the brain. "Among these genes, such as Fabp5, Spp1, and Arg1, has been found in stroke-associated macrophages, foamy macrophages in atherosclerotic plaques, and lipid-associated macrophages in myocardial infarct." (PMID 40777042, 2025). "On the protein level, microglia in the non-nodular (NA)WM rarely expressed FABP5, DAGLB, IAH1, or STARD13, and microglia nodules in MS compared to in stroke were more often FABP5+, DAGLB+, or STARD13+." (PMID 38396116, 2024). "RNAScope validated the cross-platform analysis and confirmed that astrocytes contribute to an Apoe, Cd81, and Fabp5-rich signature within the stroke infarct site." (PMID 38383565, 2024). "Altogether, this suggests that Apoe and Fabp5 play important roles in astrocytes to influence stroke recovery." (PMID 38383565, 2024). "The genes Apoe, Cd81, and Fabp5 showed complementarity in enrichment in the stroke infarct site in the subacute stage across all four platforms." (PMID 38383565, 2024). "The 10X Visium, 10X Chromium, and tDISCO analyses generated a list of interesting candidate transcripts that appeared to be differentially expressed in astrocytes proximal and distal to stroke injury, including the candidate genes, Apoe, Fabp5, Clu, Aldoc, and Cd81." (PMID 38383565, 2024). "Notably, immunodetection of FABP5 in mouse stroke penumbra and in hypoxic postmortem patients was distinctly associated with hypoxically damaged neurons." (PMID 38653992, 2024). "Collectively, these discoveries synergize with established targets such as ACSL4 and FABP5, to map a dynamic interplay of redox imbalance, metabolic dysregulation, and cell-type-specific vulnerability, thereby advancing therapeutic strategies for ferroptosis modulation in stroke." (PMID 41306421, 2025). "The percentage of HLA+ cells that were also FABP5+, DAGLB+, STARD13 or IAH1+ was similar for MS and stroke (NA)WM." (PMID 38396116, 2024).